CCL4 (C-C motif chemokine ligand 4)
Diseases named in the same sentence as CCL4 in open-access papers (continued):
Sharing a sentence is not in itself a finding about the gene and the disease.
Sepsis (25 papers, 2012 to 2025). Sepsis is defined as life-threatening organ dysfunction caused by a dysregulated host response to infection. "Remarkably, the six sepsis-elevated genes in the lungs (Il10, Tnf, Ccl3, Ccl4, Ccl12, and Nos1) were more susceptible to the nuclear blockade with the NTCI than their homologs in the kidneys." (PMID 37638006, 2023). "In addition, CCL3 and CCL4 are associated with microRNA involvement in sepsis-associated immune responses." (PMID 36225326, 2022). "Recent studies have further elucidated the roles of key downregulated genes-Ccl4, Ccr7, and Ebi3-in inflammation and sepsis-induced cardiac injury." (PMID 41169382, 2025). "Specific pro-inflammatory cytokines, including IL-1β, CCL4, CCL5, and CXCL10, have emerged as potential diagnostic markers for sepsis and critical indicators of cytokine storm severity." (PMID 38496165, 2024). "Other studies have identified the use of IL-1β, CCL4, CCL5 and CXCL10 as possible diagnostic markers for sepsis." (PMID 35811678, 2022). "Our study revealed that basil polysaccharide can significantly increase the level of CCL4 in the lungs of sepsis-induced secondary S. aureus pneumonia mice." (PMID 34054345, 2021). "The chemokine CCL4 is also an active player in the inflammatory response and chemotaxis during sepsis." (PMID 29681903, 2018). "Therefore, we investigated the role of CCL4 in the sepsis-induced secondary S. aureus pneumonia mouse model." (PMID 34054345, 2021). "Therefore, we investigated the role of CCL4 in sepsis-induced secondary S. aureus pneumonia mouse model." (PMID 34054345, 2021). "Observed disparities in expression of the DEG, e.g., high average disparity in murine and pediatric sepsis samples for the CCL4 and MARCKSL1 genes, may reflect a bias within the mapping or the underlying genomic features." (PMID 23024636, 2012). "Notably, the authors showed that mice with SOCS3-deficient macrophages experienced exacerbated Lipopolysaccharide (LPS)-induced sepsis, which was associated with enhanced JAK/STAT pathway activation and increased plasma levels of cytokines/chemokines such as CCL4." (PMID 40586774, 2025). "Through transcriptome analysis of sepsis patients, we identified significant immune suppression in the SP subgroup, as evidenced by the reduced levels of key cytokines such as IL1B and CCL4 in PBMCs." (PMID 39438692, 2024). "Pro-inflammatory cytokines, including interleukin-1β (IL-1β), CCL4, CCL5, and CXCL10, have emerged as potential biomarkers with significant implications for diagnosing sepsis and assessing the severity of cytokine storms." (PMID 38496165, 2024). "The correlation matrices in the sepsis group produced a single cluster showing a positive interaction among the pro-inflammatory mediators (CCL3, CCL4, IL1β, IL-6 and TNFα)." (PMID 35811678, 2022). "There was a clustering of CXCL8, TNFα, CCL4, CCL3, IL-1β and IL-6in the sepsis group indicating a chronic inflammatory response which seems to be mediated mostly by monocytes, whereas the febrile controls had no specific pattern." (PMID 35811678, 2022). "Comparison of molecules between the control and sepsis groups revealed statistically significant differences, except for IFN-α, IL-1RA, IL-1β, IL-2, IL-6, IL-7, IL-15, LIF, GM-CSF, TNF-α, CCL4, CCL5, and CXCL12." (PMID 31583025, 2019). "Importantly, the levels of CCL4, CCL5 and CXCL10 have been reported to be increased in both sepsis and malaria." (PMID 35811678, 2022). "Similar to IL-10-stimulated cells, neutrophils stimulated by LPS or primed by TNF-α in vitro, as well as from the patients with sepsis or NMOSD, also released VEGF, but with a different pattern of chemokines (IL-8, CCL4, CCL5) and cytokines (IL-2, -5, -9, -15, -17, TNF-α) promoting inflammation." (PMID 35757755, 2022). "Additionally, using an ROC curve analysis, the plasma levels of IL-1β, IL-7, IL-12, IL-1RA, RANTES/CCL5, MIP1B/CCL4 and IP10/CXCL10 could help differentiate children with sepsis from both clinical malaria and febrile controls." (PMID 35811678, 2022).
asthma (24 papers, 2009 to 2025). "In addition, CCL4 was significantly associated with a mix of lymphocytes, including Th1, Th2, Th9, and Th17, in severe asthma patients." (PMID 35743888, 2022). "As reported, IL-4, IL-5, and IL-13 are proinflammatory cytokines; eotaxin is a pivotal chemokine crucial for eosinophil homing to the lungs of asthma patients; and CCL4, CCL5, MCP-1, and GM-CSF recruit macrophages." (PMID 40050290, 2025). "More importantly, serum CCL-3 and CCL-4 were identified as ideal biomarkers for predicting a favorable SNOT-22 score in response to omalizumab in CRSwNP patients with asthma." (PMID 39758936, 2025). "The airway epithelium expresses CCL2, CCL3, CCL4, CCL5, CCL11, and CXCL5, which are associated with asthma." (PMID 35743888, 2022). "Consistent with unchanged T cell Ccl4 levels following experimental asthma induction, Mdk levels were similar in OVA- and HDM-treated Nf1OPG mice relative to controls, and Mdk does not induce Ccl5 production in microglia." (PMID 34880260, 2021). "MIP-1β (CCL4) is a neutrophil chemoattractant that contributes to both early and late phase asthma responses." (PMID 26010737, 2015). "Indeed, in our hands, SARS-CoV-2 infection alone led to an increased release of inflammasome-dependent and independent proinflammatory cytokines such as IL-18 and IL-33, respectively, as well as to the decrease of anti-viral CCL4 in controls and in asthma." (PMID 37087523, 2023). "However, CCL4 was increased in BALF samples from patients with corticosteroid resistant asthma, and treatment with dupilumab is recommended for oral corticosteroid-dependent severe asthma, consistent with our findings." (PMID 35892679, 2022). "Next, to determine whether experimental asthma attenuates the increase in Ccl4 and Ccl5 expression observed in the optic nerves of Nf1OPG mice at 12 and 24 weeks of age, quantitative real-time PCR was performed." (PMID 34880260, 2021). "We speculate that IL2RG and CCL4, which are also involved in this pathway, might be critical genes related to childhood specific asthma, and together with CCL2 play a role in this disease." (PMID 34525985, 2021). "The chemokines CCL3, CCL4, and CCL5 are all associated with the migration of macrophages and other leukocytes through their binding to CCR1, CCR4, and CCR5, and have been linked with asthma." (PMID 31024538, 2019). "In addition, chemokines secreted by monocytes, e.g. CXCL2, or chemoattractants for monocytes, CCL4, were both elevated in CR, implying a plausible role of monocytes in the pathology of asthma." (PMID 30038057, 2018). "In addition to finding increased expression of JAK1 in unstimulated cells of SA, we found high expression of pro-inflammatory genes including IL32, a cytokine with pro-inflammatory and antiviral activity; genes involved in Th2 inflammation; and CCL4, involved in asthma exacerbations." (PMID 33902571, 2021). "We examined serum chemokine (CCL4, CCL11, CCL26, and CCL17) and total IgE serum levels, fractionated exhaled nitrogen oxide (FENO), and CCL4 expression in nasal polyps in patients with severe ECRS and asthma." (PMID 35892679, 2022). "The most influential nodes (Fn1, Igf1, Ccl2, C3, Timp1, Cxcl12, Ccl4, Ccr2, Spp1, C3ar1, Cat, Cyp2e1, Muc5ac, Muc5b) were selected for further validation in the OVA-induced asthma and post-asthmatic fibrosis murine model." (PMID 35625754, 2022). "To ascertain the mechanisms underlying GLCCI1-mediated regulation of the effects of GCs on chemokines, we began by assessing asthma-related pro-inflammatory chemokines (CCL2, CCL3, CCL4, and CCL7) in lung tissues by RT-PCR." (PMID 34504850, 2021). "The addition of LL-37 (2 and 10 μg/ml) in eosinophil cultures did not affect the surface expression of adhesion molecules ICAM-1/CD18 or the release of asthma-related inflammatory IL-6, CXCL8 and CCL4." (PMID 28500314, 2017).
asthma (continued). "The sputum inflammatory mediator profiles were distinct with increased TH2 (IL-5, IL-13, and CCL26) and TH1 mediators (CXCL10 and 11) in severe asthma compared with COPD and increased IL-6, CCL2, CCL3, and CCL4 in COPD compared with severe asthma." (PMID 25129678, 2015). "We found that the following chemokines were significantly up-regulated in the serum in asthma compared to healthy subjects CCL2, CCL4, CCL11 and CCL13 (p < 0.05)." (PMID 19602238, 2009). "The levels of interferon‐γ (IFN‐γ), tumor necrosis factor‐a (TNF‐α), chemokine CCL22 (CCL22), interleukin 12 (IL‐12), chemokine CCL4 (CCL4), chemokine CCL2 (CCL2), and chemokine CCL13 (CCL13)were significantly higher in the acute asthma group than in the stable asthma group." (PMID 39508721, 2024). "Additionally, we examined the levels of inflammatory cytokines in sputum and found that IL‐5, IL‐6, IL‐8, TNF‐α, IFN‐γ, CCL17, CCL22, CXCL10, CCL4, CCL2, IL‐4, IL‐13, and CCL26 were significantly lower in stable asthma than in acute asthma." (PMID 39508721, 2024). "Although it was previously reported that patients with severe asthma who were responded to mepolizumab had lower CCL4 levels when compared with non-responders, this observation was largely inconclusive due to a small sample size." (PMID 35892679, 2022). "The findings reveal that experimental asthma induction impairs microglia Ccl5 support of optic glioma formation and growth without altering T-cell Ccl4 expression." (PMID 34880260, 2021). "An increase in CCL4 was evident in the never smokers with asthma (31.6 pg/ml (4.6, 58.5), p = 0.03)." (PMID 23951170, 2013). "Since T cell Ccl4 levels were not reduced by experimental asthma induction, we hypothesized that OVA- and HDM-treated Nf1OPG mouse T cells might produce an inhibitor of microglia Ccl5 production." (PMID 34880260, 2021). "CCL-3 and CCL-4 in serum and IgE, CXCL-1, GM-CSF, and IP-10 in nasal secretion may be considered as preferable biomarkers for predicting favorable or ineffective response to omalizumab therapy in patients with refractory CRSwNP comorbid with asthma, based on various clinical indicators." (PMID 39758936, 2025). "Few sputum cytokine concentrations changed in response to dexamethasone IL-17 and IFNα increased in smokers, CCL4 increased in never smokers and CCL5 and CXCL10 reduced in ex-smokers with asthma." (PMID 23951170, 2013).
fibrosis (19 papers, 2010 to 2025). the formation of excess fibrous connective tissue in an organ or tissue in a reparative or reactive process. "In contrast, i.p., pre-and post-treatment of CCL4/mice with P. pavonica extracts showed a marked decrease in periportal hepatic fibrosis and prominent hepatic regeneration." (PMID 39910080, 2025). "IHC revealed that H3K36me3 staining was obviously reduced in intrahepatic nonparenchymal cells around the portal area of liver tissue in the CCL4-induced fibrosis model." (PMID 40651612, 2025). "The efficacy of PPAR α/δ dual agonist GFT505 had been evaluated in several animal models previously, including western diet-fed human APOE2 transgenic mice, MCD diet-fed db/db mice and CCL4-induced fibrosis rats." (PMID 33326461, 2020). "In the present study, we established a stable mouse model with a fibrosis background using chronic subcutaneous injection of CCL4." (PMID 26517671, 2015). "Moreover, the deficiency of MYD88 signaling in B cells decreased the infiltration of dendritic cells and monocytes in CCL4-induced fibrosis mice." (PMID 38287425, 2024). "We found an induction of HIF-2α in CCL4-injected liver injury and fibrosis mouse models." (PMID 39684823, 2024). "In addition, CCL5 and its related CCR5 ligand CCL3 and CCL4 are upregulated in the liver of patients with fibrosis." (PMID 33623529, 2021). "There have been many researches trying to reverse the liver cirrhosis in animal models such as studies on the preventive effect of curcumin on liver cirrhosis induction in rat models by CCL4, which revealed that daily oral administration of curcumin improves liver cirrhosis and fibrosis." (PMID 33145022, 2020). "A further study showed that hepatic expression of dectin-1 was upregulated in a thioacetamide (TAA)/CCL4 fibrosis mouse model, and that dectin-1 negatively regulated the expression of TLR4 and its co-receptor CD14 to mitigate fibrosis development and hepatic inflammation." (PMID 31717860, 2019). "Previous work reported that the transient DT-induced Treg depletion in the late phase of chronic CCL4 treatment resulted in aggravated liver damage and fibrosis, suggestive that with chronic damage, the situation could be different to our observations in acute damage." (PMID 36389734, 2022).
psoriasis (19 papers, 2010 to 2025). An autoimmune condition characterized by red, well-delineated plaques with silvery scales that are usually on the extensor surfaces and scalp. "We had found L-THE regulated chemokine signaling pathway and IL-17A signaling pathway associated genes, such as CXCL2, CCL3 and CCL4 in skin tissues from mice with psoriasis." (PMID 34381369, 2021). "Beyond its involvement in metabolic diseases and cancers, CCL4 plays a role in the development of systemic lupus erythematosus, multiple sclerosis, multiple myeloma, psoriasis, cystic fibrosis, and sarcoidosis." (PMID 39813538, 2025). "Serum CCL22/MDC and CCL4/MIP-1β levels also were elevated at baseline in the psoriasis study population versus healthy controls." (PMID 39114670, 2024). "Cells within a single CD8 TEM cluster enriched among PSO subjects (cluster 11) showed a strong upregulation of CCL4, a CD8+ T cell recruiting chemokine associated with psoriasis, along with other inflammatory cytokines and chemokines (TNF, IFNG, CCL3, CCL4L2)." (PMID 35309349, 2022). "In our cohort, the inflammatory cytokine CCL4 is another major signature molecule that discriminates between psoriasis patients and healthy subjects." (PMID 34006909, 2021). "In serum, a significant increase of IL-1ra (p = 0.02), IL-6 (p = 0.01), as well as CCL4 (p = 0.03) was observed in psoriasis patients compared with healthy subjects." (PMID 34006909, 2021). "CCL4/CCL4L is known to promote immune cell infiltration in psoriasis, including T helper type-1 cells, regulatory T cells, monocytes, and dendritic cells." (PMID 29599774, 2018). "In T cells, NFATc1 stimulates the expression of several genes that are highly expressed during psoriasis, as the Ccl3 and Ccl4 chemokine genes." (PMID 27222343, 2016). "In psoriasis, CCL4, GZMK and KLRF1 show significantly higher, while ADM, ANXA3, IL4, MMP9 and OLR1 show significantly lower expression levels in patients with arthritis negative psoriasis compared to patients with symptoms of arthritis." (PMID 20444268, 2010). "Oral administration of genistein in psoriasis patients for 8 weeks impaired the transcription of genes overexpressed in psoriasis, CXCL10, IL-6, STAT3, NFKB1, CCL4 while stimulated the transcription of gene repressed in psoriasis, IL-1RN in peripheral blood cells or lesional skin." (PMID 32751360, 2020). "CCL4L2, a ligand for CCR1 and CCR5 on macrophages and monocytes, is a polymorphism of CCL4L1, itself a non-allelic copy of CCL4 that differs in a single amino acid and all of which are associated with psoriasis severity." (PMID 29534074, 2018). "An increment of ≥3 copies in the CNVs of CCL4/CCL4L is associated with psoriasis severity, whereas moderate disease correlated with a lower CNV (≤2 copies); specifically, the CCL4L1 allele frequency is higher in severe psoriasis, whereas CCL4L2 is more frequent in patients with milder disease." (PMID 36143237, 2022). "The integration of metabolic and immune data indicated a molecular signature constituted by IL-6, IL1-ra, DMG, CCL4, Ile, Gly and IL-8, which could discriminate patients and healthy subjects and could represent a candidate tool in the diagnosis of new-onset psoriasis." (PMID 34006909, 2021). "Proteins related to the central disease‐driving pathways of psoriasis, namely the TH1 (CCL3, CCL4, CXCL9, CXCL10, CXCL11, TNFα) and TH17 pathway (CXCL1, CCL20, IL‐17A, IL‐12B) were found elevated in lesional skin across both studies." (PMID 40970551, 2025). "The heatmap showed that C–C motif chemokine ligands (Ccl3, Ccl4, Ccl5, Ccl17, Ccl19-Ps2, and Ccl22) were expressed at higher levels in IMQ-induced psoriasis." (PMID 38566145, 2024). "From the t-test between serum metabolites and cytokines from psoriasis patients and healthy volunteers, seven candidate signature molecules were obtained: DMG, Gly and Ile, together with IL-6, CCL4, IL1-ra, and IL-8." (PMID 34006909, 2021).
liver cirrhosis (18 papers, 2014 to 2025). "In 1996, Nakano also proposed using carbon tetrachloride (CCL4) and TAA to establish liver cirrhosis models, as TAA and CCL4 induced liver cirrhosis can cause osteodystrophy, which is mainly responsible for bone volume reduction." (PMID 35526079, 2022). "The preset research also reported a novel liver cirrhosis model by coadministration of CCL4/urethane." (PMID 35328564, 2022). "In the present study, we used mesenchymal stem cells derived from the mesenteric fat to treat the liver cirrhosis induced by CCL4 in a period of 16 weeks." (PMID 33145022, 2020). "To further investigate the effect of autophagy on specific RDCs of interest, we used EpCAM-positive selection to purify RDCs from a rat model of AAF/CCL4-induced liver cirrhosis." (PMID 32197543, 2020). "The purpose of this study was to evaluate the regenerative potential of mesenteric fat stem cells in CCL4-induced liver cirrhosis in an animal model." (PMID 33145022, 2020). "Hepatocytes are the major sources of matrix metalloproteinases (MMP), and their inhibitors are involved in liver extracellular cell matrix (ECM) deposition, which is involved in the pathogenesis of liver cirrhosis in CCL4-induced liver cirrhosis in rats." (PMID 29137226, 2017). "A novel rat model for liver cirrhosis was developed by CCL4/Urethane co-administration." (PMID 35328564, 2022). "Liver cirrhosis was induced by IP injection of CCL4 for 16 weeks in rats." (PMID 33145022, 2020). "After 6 weeks of CCL4 administration, rats developed liver cirrhosis with ascites." (PMID 26152281, 2015). "A mouse model of liver cirrhosis was established using a CCL4-induced method, and a multifaceted approach was employed to elucidate the mechanism of action of JQC in the treatment of liver cirrhosis." (PMID 41383461, 2025). "Patients with liver cirrhosis often exhibit increased levels of CCL5, along with related chemokines CCL3 and CCL4." (PMID 38338668, 2024). "CXCL10, CXCL11, CCL3, CCL4 and liver cirrhosis were the predictive factors for non-NR by univariate logistic analysis, but only the CCL4 was the independent predictor for non-NR by multivariate logistic analysis." (PMID 29284412, 2017). "By univariate logistic regression analysis, rs12979860 CC genotype, CXCL10, CXCL11, CCL3, CCL4 and liver cirrhosis were the factors for non-NR." (PMID 29284412, 2017).